TTR (transthyretin)
Diseases named in the same sentence as TTR in open-access papers (continued):
Sharing a sentence is not in itself a finding about the gene and the disease.
amyloidosis (continued). "This patient, who is, to the best of our knowledge, the first patient with TTR Phe84Ser amyloidosis demonstrated by electrophysiological examination, had multiple cranial neuropathy, including the second, third, seventh, ninth, and tenth nerve palsy." (PMID 35795194, 2022). "In a clinical trial for Transthyretin amyloidosis gene therapy [NCT04601051], lipid nanoparticles have efficiently been used for in vivo delivery of a CRISPR-Cas9 system resulting in transthyretin (TTR) protein disruption." (PMID 36553489, 2022). "Wild-type transthyretin amyloidosis with cardiac involvement (ATTRwt-CA) is an infiltrative and progressive disorder caused by the extracellular deposition of transthyretin amyloid fibrils in the heart in the absence of causal mutations." (PMID 35440973, 2022). "The first siRNA drug, ONPATTRO® (Alnylam Pharmaceuticals Inc.), which was approved by FDA in 2018 for treating hereditary transthyretin-mediated amyloidosis, contains the ionizable lipid MC3 in its LNP formulation." (PMID 36140280, 2022). "In contrast with other ASYN‐focused agents in development, UCB0599 binds and stabilizes unfolded ASYN and therefore has a similar approach to that of tafamidis on transthyretin, shown to slow disease progression of hereditary transthyretin amyloidosis." (PMID 35959805, 2022). "The other most common amyloidosis affecting the heart would be transthyretin (TTR)‐related amyloidosis (ATTR)." (PMID 35567784, 2022). "It is a therapeutic RNA interference (RNAi) product that is used for the treatment of hereditary transthyretin (TTR)-mediated amyloidosis (hATTR) in adults." (PMID 36015165, 2022). "The survival of patients after diagnosis varies, depending on the type of amyloidosis, with a survival time of approximately 60 months in TTR-related amyloidosis." (PMID 35897655, 2022). "Boronic acid-substituted stilbenes have been investigated as ligands for transtherytin (TTR) to stabilize the homotetramer, preventing fibril formation that leads to amyloidosis." (PMID 35337063, 2022). "Pertinent studies were searched in PubMed/Medline (updated February 2022) using the following terms: “transthyretin amyloidosis”, “seeding”, “seed”, “Amyloid seeds”." (PMID 35386059, 2022). "A previous study that analyzed hereditary TTR amyloidosis showed a similar result, with very high inpatient cost compared to outpatient cost, although the slope of the trend in our study was slightly different." (PMID 35840997, 2022). "Age‐related wild‐type transthyretin amyloidosis (wtATTR) is characterized by systemic deposition of amyloidogenic fibrils of misfolded transthyretin (TTR) in the connective tissue of many organs." (PMID 35262277, 2022). "It makes up about 23% of TTR amyloidosis cases, with more than 85% of those individuals being African American." (PMID 35959393, 2022). "In contrast, with regard to the amyloid fibril formation mechanism of ATTRv amyloidosis, the dissociation of TTR tetramers into TTR monomers has been well documented as a rate-limiting step to amyloid fibril formation." (PMID 35893595, 2022). "The number of elderly patients affected by wild type TTR amyloidosis suggests that the category of TTR amyloidosis is moving from a rare to a common disease." (PMID 35237660, 2022). "CA most frequently occurs when misfolded aggregates of either immunoglobulin light chains (AL) amyloidosis or transthyretin (ATTR) amyloidosis deposit within cardiac tissue." (PMID 34996915, 2022). "Over the past years, multiple research was conducted on TTR to resolve its participation in few amyloid diseases such as central nervous system amyloidosis (CNSA), senile systemic amyloidosis (SSA), and familial amyloid cardiomyopathy (FAC)." (PMID 36009368, 2022).
amyloidosis (continued). "When the stability of the tetrameric structure is lost, it breaks down, paving the way for the aggregation of TTR monomers into insoluble fibrils leading to transthyretin (ATTR) amyloidosis, a progressive disorder mainly affecting the heart and nervous system." (PMID 36009453, 2022). "Onpattro® (patisiran) is a siRNA product aiming to treat the rare hereditary disease transthyretin-mediated amyloidosis, in adult patients." (PMID 36401279, 2022). "In all amyloidosis referral centers, we are observing a substantial increase in the prevalence of wild-type transthyretin (ATTRwt) cardiomyopathy, which is now becoming the most common form of cardiac amyloidosis." (PMID 36555787, 2022). "In June-2021, APOLLO-B was enrolled for phase III study of patisiran for the treatment of TTR-mediated Amyloidosis (ATTR) with patients having cardiomyopathy." (PMID 35352626, 2022). "Transthyretin protein (TTR) and light chain (AL) amyloidosis are the most common types of cardiac amyloidosis." (PMID 36290299, 2022). "There have been advances in the effective treatment of TTR amyloidosis with the regulatory agency approvals of the TTR stabilizer, tafamidis; approved in the early 2010s for TTR familial polyneuropathy and, the late 2010s for TTR cardiomyopathy." (PMID 35810311, 2022). "Tafamidis is now in the market for the treatment of TTR related amyloidoses and other compounds are in clinical trials such as acoramidis or in the pipeline for being tested in clinical studies." (PMID 35237660, 2022). "Hereditary transthyretin (ATTRv) amyloidosis is a rare, genetically heterogeneous and phenotypically variable systemic disease characterized by deposition of misfolded transthyretin fibrils in various tissues." (PMID 36494773, 2022). "The extracellular aggregation of destabilized transthyretin (TTR) variants is implicated in the onset and pathogenesis of familial TTR-related amyloid diseases." (PMID 35626697, 2022). "Patisiran (ONPATTRO®), the first Food and Drug Administration (FDA) approved LNP-formulated siRNA drug, has reduced the formation of transthyretin protein in the liver and has been used to treat hereditary transthyretin-mediated amyloidosis since 2018." (PMID 36438494, 2022). "Subsequently, Alnylam Pharmaceuticals’ liposomal siRNA drug ONPATTRO® (Cambridge, MA, United States) for hereditary transthyretin-mediated amyloidosis was approved by the FDA in 2018." (PMID 36140280, 2022). "Many small molecule kinetic stabilizers have been reported to inhibit TTR-related amyloidosis and some have been approved for clinical applications or clinical trials, such as Tafamidis, Diflunisal, and AG10." (PMID 36311011, 2022). "This is in line with a previous study that demonstrated a reduction in existing TTR deposits in a transgenic mouse model of TTR-mediated amyloidosis (ATTR amyloidosis) after siRNA-mediated knockdown of TTR." (PMID 35269571, 2022). "Twelve years later, the first LNP-siRNA drug (Patisiran) was authorized by the FDA to treat hereditary transthyretin-mediated amyloidosis." (PMID 36432711, 2022). "Cardiac amyloidosis (CA) occurs mainly in primary light-chain (AL) amyloidosis, hereditary transthyretin (ATTRv) amyloidosis and senile or wild-type transthyretin (ATTRwt) amyloidosis." (PMID 35204645, 2022). "So far, more than 130 destabilized mutations on the TTR gene have been reported, most of which can lead to TTR amyloidosis." (PMID 36311011, 2022). "The diagnosis of TTR-amyloidosis is challenging for the clinician and requires their heightened awareness." (PMID 35925120, 2022). "The first was the MC3-LNP, also known as Onpattro, a first-ever siRNA therapeutic developed by Alnylam pharmaceuticals for the treatment of transthyretin (TTR) amyloidosis." (PMID 36015198, 2022). "Patisiran is an siRNA enveloped in lipid NPs, which inhibits the hepatic synthesis of transthyretin (TTR) and improves several clinical manifestations of hereditary TTR-mediated amyloidosis (HTA)." (PMID 35057033, 2022).
amyloidosis (continued). "Patisiran (ONPATTRO) is the first siRNA drug approved in 2018 for the treatment of polyneuropathy of hereditary transthyretin-mediated (hATTR) amyloidosis." (PMID 35352626, 2022). "Over 30 different human precursor proteins can form amyloid fibrils, but the overwhelming majority of CA cases result from misfolded immunoglobulin light-chain (light-chain amyloidosis [AL]) and transthyretin (transthyretin amyloidosis [ATTR]) proteins." (PMID 35524881, 2022). "CMR is the reference standard imaging test for the diagnosis of cardiac amyloid, but cannot differentiate between AL and TTR amyloid." (PMID 33000405, 2022). "Transglutaminase antibodies (Celiac disease), abdominal fat biopsy and TTR gene sequencing (Amyloidosis) were normal." (PMID 33732874, 2021). "In the present analysis genes that are known to be mutated in human inherited amyloidosis forms, such as APP, and TTR had variants matching the reference sequence." (PMID 33863921, 2021). "Structural elucidation of TTR at various intermediate states is necessary to understand the structural mechanism of TTR amyloidosis in detail." (PMID 33922648, 2021). "Systemic forms of amyloidosis affecting the heart are mostly light-chain (AL) and transthyretin (ATTR) amyloidoses." (PMID 33459839, 2021). "In comparison, a series of studies proposed that proteolysis plays a more direct role in TTR amyloidosis." (PMID 33922648, 2021). "This study will stimulate the cardiologists to carry a systematic approach to diagnose wild-type transthyretin-related amyloidosis not only in elderly but in young patients as well." (PMID 33907095, 2021). "In the present study, we showed an impairment in the production of several chemokines in the peripheral nervous system of a pre-clinical model of TTR V30M amyloidosis." (PMID 34093538, 2021). "In this review, we discuss recent advancements in the structural understanding of TTR misfolding and amyloidosis processes." (PMID 33922648, 2021). "In particular, the proteolysis-induced amyloidosis mechanism of TTR has attracted much attention in recent years, and various structural studies have revealed the mechanistic details of this amyloidosis process." (PMID 33922648, 2021). "The most widely used ATTR amyloidosis therapeutics either reduce transthyretin production (inotersen and patisiran) or stabilize the tetramer (tafamidis)." (PMID 34729532, 2021). "Since the identification of TTR in human amyloid deposits in the 1970s, TTR amyloidosis has been shown to be strongly correlated with several amyloidoses." (PMID 33922648, 2021). "Tafamidis is an exception since it has been used with great success in several countries in recent years to treat patients with familial amyloid polyneuropathy, a transthyretin (TTR)-related amyloidosis, and more recently, familial cardiomyopathy." (PMID 34594185, 2021). "Because 95% of plasma TTR is synthesized from liver, liver transplantation was firstly proved as the only potentially curative treatment for TTR amyloidosis in 1990s." (PMID 33679409, 2021). "Any patient with TTR amyloidosis should have gene sequencing of the TTR gene to distinguish wild-type TTR, as is seen in senile cardiac amyloidosis, from the very rare mutations of TTR that lead to inherited amyloidosis." (PMID 33993188, 2021). "To remove pre-existing ATTR from affected tissues in patients with TTR amyloidosis, we developed the human monoclonal antibody NI301A selectively targeting ATTR aggregates." (PMID 34035264, 2021). "In patient II-4, many abnormal materials were found in the interstitial tissues in the epineurium and the existence of TTR-related amyloid deposits was proved by Congo-red staining, polarized light with “apple-green” and TTR immunohistochemical staining." (PMID 35185758, 2021). "Our TTR aggregation assays provided consistent results showing that GC-1 is the most efficient inhibitor of TTR amyloidosis." (PMID 33800546, 2021).
amyloidosis (continued). "Given the social and emotional toll of TTR amyloidosis, multidisciplinary teams of healthcare professionals also need to coordinate with families because of their importance in helping patients adapt to changes in their functioning and coping strategies." (PMID 33557882, 2021). "Amyloid-β peptide, prion protein, α-synuclein, and transthyretin (TTR) are examples of the more than 40 different human peptides and proteins identified in amyloid deposits that are at the origin of the known amyloidoses." (PMID 35008816, 2021). "We report here 18 subjects affected by hATTR amyloidosis treated with patisiran, a small interfering RNA acting as TTR silencer, and evaluated with a PND score, the NIS and NIS-LL scale, and a Norfolk QOL-DN questionnaire at baseline and then every 6 months." (PMID 33921571, 2021). "Recently, a high-resolution structure of amyloid fibrils from the heart of a patient with ATTRv Val30Met amyloidosis provided the first insights of how natively folded TTR protein changes its shape to become incorporated into a single amyloid protofilament." (PMID 34880242, 2021). "Our observations provide strong evidence that the thyromimetic ligands tested here are highly attractive candidates as potent inhibitors of TTR amyloidosis." (PMID 33800546, 2021). "Here, we further explored the functional capabilities of these thyromimetics to inhibit transthyretin (TTR) amyloidosis." (PMID 33800546, 2021). "Amyloid transthyretin (ATTR) amyloidosis is characterized by the abnormal accumulation of ATTR fibrils in multiple organs." (PMID 34880242, 2021). "The relevant concern in patients with long survival after LT is cerebral amyloid angiopathy, due to leptomeningeal TTR amyloid infiltration, which leads to possible cognitive decline." (PMID 34206500, 2021). "Liver transplantation (LT) and combined heart–liver transplantation represented the first specific therapy for hATTR amyloidosis, suppressing the main source of mutant TTR." (PMID 33921571, 2021). "Extracellular misfolding and misassembly of TTR lead to the formation and accumulation of amyloid fibrils in a variety of tissues, which gives rise to distinct progressive clinical syndromes known as TTR-related amyloidosis." (PMID 34343569, 2021). "A complete understanding of the molecular mechanisms subserving the development of TTR amyloidosis will provide useful insights into the heterogenic manifestations of this misfolding disease." (PMID 34884963, 2021). "Patisiran is an siRNA that targets transthyretin transcripts as a therapy for hereditary transthyretin (hATTR)‐mediated amyloidosis." (PMID 32391605, 2021). "Oral TTR stabilizers presently include tafamidis, which represent the first drug approved for ATTRv amyloidosis, and diflunisal, both binding to the TTR thyroxine binding sites." (PMID 34206500, 2021). "The major types of amyloidosis are light chain (AL), transthyretin-derived (ATTR) amyloidosis, and secondary amyloidosis (AA)." (PMID 34106429, 2021). "According to these studies, the stability of the DAGH β-sheet, one of the two main β-sheets in TTR, is a crucial determinant of the TTR amyloidosis mechanism." (PMID 34746240, 2021). "Protein abnormal folding, characteristic of amyloidosis, most often concerns the transthyretin protein (TRT) and the immunoglobulin light chain." (PMID 34641582, 2021). "The two predominant amyloid proteins found in the heart are transthyretin (ATTR) and immunoglobulin light chain (AL), with ATTR amyloidosis the most prevalent form in patients with AS." (PMID 34575344, 2021). "Compounds such as Inotersen act through the first mechanism category by targeting the TTR gene involved in hereditary transthyretin-mediated amyloidosis (OMIM 105210), leading to the degradation of mutant mRNA." (PMID 34830104, 2021). "Due to the relative predominance of TTR in human serum and cerebrospinal fluid, TTR amyloidosis results in detrimental amyloidogenic diseases." (PMID 33800546, 2021).
amyloidosis (continued). "There are many different types of amyloidosis with light-chain (AL) amyloidosis and transthyretin (ATTR) amyloidosis being the most common types of cardiac amyloidosis." (PMID 34070853, 2021). "Transthyretin (TTR) amyloidosis is a systemic disease characterized by the accumulation of TTR amyloid (ATTR) in myocardium, peripheral nerves, and various other tissues, causing congestive heart failure, polyneuropathy, and death." (PMID 34035264, 2021). "Still, after cardiac transplantation in patients with ATTv amyloidosis, the amyloid deposition progresses utilizing wild-type TTR." (PMID 34884963, 2021). "It was subsequently demonstrated that the amount of amyloid present in TTR- and tau-transgenic mice was reduced by curcumin supplementation." (PMID 33496266, 2021). "In August 2018, the first-ever RNAi-based drug, Alnylam’s Patisiran, was approved by the U.S. Food and Drug Administration (FDA) for treating transthyretin amyloidosis by inhibiting hepatic transthyretin production." (PMID 34578632, 2021). "In contrast, it was also proposed that subtilisin, a serine protease from Bacillus subtilis, is responsible for TTR proteolysis and subsequent amyloidosis." (PMID 33922648, 2021). "Type B TTR is the main component in patients with ATTRv amyloidosis, whereas type A fibrils are found in ATTRv and WT amyloidosis." (PMID 34884963, 2021). "To date, three siRNA drugs to treat porphyria, Transthyretin (TTR) amyloidosis and very recently hyperlipidemia have been approved by FDA for clinical use." (PMID 34522211, 2021). "The recent approval of the first-ever siRNA-based drug of the treatment of a neurological disease, hereditary transthyretin-mediated amyloidosis, has paved the way for a new therapeutic approach based on post-transcriptional disease gene silencing." (PMID 33750896, 2021). "For example, two therapeutics based on RNA interference (RNAi) were approved, ONPATTRO® (Partisiran) for polyneuropathy in hereditary transthyretin-mediated (hATTR) amyloidosis in 2018, and GIVLAARITM (Givosiran) for acute hepatic porphyria (AHP) in 2019." (PMID 34065544, 2021). "The second most common type is the wild-type form of transthyretin amyloidosis (ATTR) which is being recognized increasingly." (PMID 34254119, 2021). "In 2018, the first LNP containing drug, Onpattro®, the LNP-siRNA orphan medicinal product for the treatment of transthyretin-mediated amyloidosis, was approved." (PMID 34068715, 2021). "Successful examples of PEGylated lipid-based nanoparticles are given by the FDA approved mRNA vaccines of BioNTech and Moderna or siRNA therapeutic ONPATTRO® for polyneuropathy in hereditary transthyretin-mediated (hATTR) amyloidosis." (PMID 34065544, 2021). "Previous works have suggested a link between TTR and VEGF, and for example, elevated VEGF was found in the vitreous of patients with TTR amyloidosis." (PMID 34429155, 2021). "Systemic forms of amyloidosis, which affect the heart, are mainly the light chain (AL) and ATTR amyloidoses, resulting from the deposition of misfolded transthyretin (either as the wild-type [ATTRwt] or mutated [ATTRv] form)." (PMID 33459839, 2021). "Recently, transthyretin amyloidosis (ATTR), has been found in around 13% of patients with HFpEF, 16% of patients with aortic stenosis and some elderly men with carpal tunnel syndrome, and can be easily diagnosed using bone scintigraphy." (PMID 34441815, 2021). "siRNA-based therapeutics for hereditary transthyretin-mediated amyloidosis and acute hepatic porphyria (AHP) have also been approved by USFDA." (PMID 34631795, 2021). "This was highlighted by the FDA approval of first siRNA “Patisiran” for the treatment of transthyretin-mediated amyloidosis disease." (PMID 33750896, 2021). "Several new drugs for the treatment of TTR amyloidosis, such as tafamidis and patisiran, recently became available, which will certainly impact future treatment." (PMID 34524619, 2021).